IGFBP7 (insulin like growth factor binding protein 7)
Diseases named in the same sentence as IGFBP7 in open-access papers (continued):
Sharing a sentence is not in itself a finding about the gene and the disease.
tumor (continued). "The xenografted tumor also shows decreased angiogenesis following tail-vein injection of recombinant IGFBP7, as demonstrated by significantly reduced CD34 and, most importantly, vascular endothelial growth factor (VEGF) expression." (PMID 32500027, 2020). "IGFBP7 downregulation in HGSC tumors was associated with reduced overall survival and poor outcome, suggesting its involvement in the tumor suppression pathway." (PMID 33019700, 2020). "Induction of pSMAD3 and IGFBP7 expression was already present in early lesions 3 weeks after tumor induction (Fig EV3C and D) and was accompanied by neutrophil infiltration (Fig EV3C)." (PMID 31793740, 2020). "IGFBP7 gene expression is clearly significantly down-regulated in human HCC tumor samples and HCC cell lines compared with healthy hepatocytes." (PMID 32500027, 2020). "Conversely, the overexpression of IGFBP7 decreases tumor growth by activating an antitumor immune response." (PMID 32500027, 2020). "Inhibition of angiogenesis, as evidenced by a decline in CD31 staining, was shown to be a major factor in the marked inhibition of tumor growth resulting from IGFBP7 overexpression in the HepG3-AEG-1 model system." (PMID 32500027, 2020). "IGFBP7 also plays a role as a tumor suppressor in the liver, urinary bladder, cervix uteri, lung, esophagus, thyroid, as well as head and neck cancer." (PMID 32500027, 2020). "Both IGFBP7 mRNA and protein expression are drastically increased during senescence of the normal epithelium of the prostatic gland, which supports the role of IGFBP7 as a tumor suppressor." (PMID 32500027, 2020). "In this respect, a role of IGFBP7 as inhibitor of the expansion and aggressiveness of tumour stem‐like cells was recently proved in vivo." (PMID 31081251, 2019). "IGFBP7-expressing CAFs have been demonstrated to promote colon cancer cell proliferation through paracrine tumor-stroma interactions in vitro." (PMID 30927930, 2019). "IGFBP7, in particular, is a secreted protein that accumulates in the basement membrane of tumor endothelial cells, and its expression is believed to be associated with higher-grade gliomas." (PMID 31544833, 2019). "IGFBP7 was reported to act as a tumor suppressor by regulating cell proliferation, invasion, and angiogenesis." (PMID 30609749, 2019). "IGFBP7-overexpressing ARO, FRO and WRO cells grew much more slowly than their corresponding vector control cells following subcutaneous inoculation, while IGFBP7-silenced WRO cells showed a much higher tumor growth rate than vector control WRO cells." (PMID 31183073, 2019). "Accumulating evidence suggests that IGFBP7 serves as a tumor suppressor in various types of cancers." (PMID 31183073, 2019). "Similar to that for many other tumor suppressors, the downregulated expression of IGFBP7 in tumor tissues is mainly ascribed to genetic and epigenetic regulation." (PMID 31183073, 2019). "Insulin-like growth factor binding protein 7 (IGFBP7) has recently been recognized as a tumor suppressor in many cancer types." (PMID 31183073, 2019). "The molecular localization of the anti-IGFBP7 sdAb in the tumor brain vessels was further demonstrated by fluorescence microscopy." (PMID 31544833, 2019). "In the gene expression microarrays, IGFBP7 – a potent tumor (and probably metastasis) suppressor in melanoma – was the gene with the highest upregulation in expression in the CEACAM1 knockdown tumors." (PMID 30089785, 2018). "As high expression of IGFBP7 is positively correlated with survival one would have to find a way to upregulate this tumor suppressor." (PMID 30089785, 2018). "In the tumor stroma microenvironment, IGFBP7 expression is closely related with the transforming growth factor beta (TGF-β secretion, which is a potent factor promoting tumor cell invasiveness and metastasis." (PMID 28191313, 2017). "We found that among the IGFBPs studied (IGFBP1–7), IGFBP7 is the only IGFBP down-regulated during tumor progression." (PMID 28882129, 2017).
tumor (continued). "In various cancer types including hepatocellular carcinoma, breast, brain, and colon, IGFBP7 can function as a tumor suppressor and have the ability to suppress proliferation, adhesion, angiogenesis, survival, or induce apoptosis and senescence." (PMID 28191313, 2017). "Another protein whose level was elevated in the tumor was insulin-like growth factor-binding protein 7 (IGFBP7) that has been recently described as a tumor stroma and epithelial-to-mesenchymal transition (EMT) marker in various epithelial cancers." (PMID 29176937, 2017). "Among the genes dysregulated as a consequence of tumour suppression, IGFBP7 exhibited a strong upregulation as measured by Affymetrix microarray analysis." (PMID 25886299, 2015). "IGFBP-7 induced the apoptosis of tumor and potentially predicted the clinical outcome in some cancers is further demonstrated." (PMID 25880247, 2015). "Although IGFBP-7 is a known tumor suppressor, CAFs expressing IGFBP-7 stimulate colony formation of co-cultured CRC cells, suggesting that IGFBP-7 indirectly promotes tumor progression through manipulation of CAFs." (PMID 25853091, 2015). "Aberrant hyper-methylation of IGFBP-7 in oral tongue tumors was significantly concomitant with tumor progression (invasive depth, loco-regional recurrence, and cancer consequence) and poor prognosis." (PMID 25880247, 2015). "After 4 h, all tumour secreted-proteins induced a significant increase in surface E-selectin at either higher concentrations tested (CC, IGFBP-7) or over the whole concentration range (CL, VEGF-A, TNF-α)." (PMID 26407999, 2015). "Another example for a tumor-stroma interaction partner is IGFBP7, which was identified as a promoter of anchorage-independent growth in malignant mesenchymal cells and in epithelial cells with an EMT phenotype." (PMID 25919140, 2015). "Our analysis of a limited number of samples by RT-PCR showed that four of eight serous samples exhibited evidence of IGFBP7 expression, where only two tumour samples showed robust expression." (PMID 25886299, 2015). "In vitro studies have been demonstrated that IGFBP-7 can induce apoptosis in many cancer cells, e.g., breast and prostate cancer cells; and acts as a potential tumor suppressor against colorectal carcinogenesis." (PMID 25880247, 2015). "Although some reports demonstrate the anti-tumor effects of IGFBP-7 including cell growth inhibition, senescence, and apoptosis, our study is evident that the down-regulation of IGFBP-7 in invasive HNSCC cell lines which show EMT feature." (PMID 25880247, 2015). "This was also evident with the tumour-secreted proteins at their chosen concentrations (CC: 146 ± 42.3 %, CL: 153 ± 33.4 %, IGFBP-7: 143 ± 28.5 %, VEGF-A: 146 ± 41.0 % and TNF-α: 122 ± 11.2 %)." (PMID 26407999, 2015). "We investigated IGFBP7 expression in tumour samples and reference surface normal epithelial cells from samples derived from our tissue banks." (PMID 25886299, 2015). "As IGFBP7 is a tumor suppressor, most research on IGFBP7 has focussed on the tumor cells themselves." (PMID 24427302, 2014). "IGFBP7-dependent tumor suppression involves induction of senescence and/or apoptosis signaling, and its expression in tumor cells is often regulated by DNA methylation, retinoic acid and transforming growth factor (TGF)β." (PMID 24690739, 2014). "At present, this is difficult to assess, because there is little research on the role of IGFBP7 in tumor stroma." (PMID 24427302, 2014). "FN1 functionally connects a pair of coexpressed glycoproteins, FBLN1 and FSTL1, and SPARC is connected to IGFBP7, a tumor suppressor, which creates a functional link between a candidate tumor suppressor, PDGFRL, and a mesenchymal factor, FSTL1." (PMID 24944582, 2014). "Why then do the tumor cells secrete factors which induce IGFBP7 which in turn suppresses their own growth?" (PMID 24427302, 2014).
tumor (continued). "Frequencies of hypomethylation of LINE-1 and hypermethylation of SLIT2, MAL and IGFBP7, defined by predetermined cut off values, were 55, 64, 46 and 54% in NSCLCs, respectively and exhibited tumor-specific features." (PMID 23381221, 2013). "IGFBP7 is expressed in normal epithelial cells and acts as a tumor suppressor by inducing apoptosis in various types of tumors." (PMID 23381221, 2013). "The expression level of IGFBP7 was even lower after co-culture of SKOV3-PM4 with HLEC, indicating that specific factors secreted by HLEC inhibited the expression of IGFBP7 in tumor cells." (PMID 24349832, 2013). "IGFBP7 is relatively abundant in ovaries compared with normal tissues, where its content in corresponding tumor tissues is low." (PMID 24349832, 2013). "The high malignancy and strong lymphatic metastasis ability of the tumor result in a low expression level of IGFBP7." (PMID 24349832, 2013). "IGFBP7 has been characterised as a tumour suppressor, acting as a secreted senescence/apoptosis factor." (PMID 21108726, 2011). "In lower-magnification images the fluorescence of injected anti-IGFBP7 sdAb-Cy5.5 was present throughout the tumour in virtually all vessels." (PMID 20959824, 2010). "Secondly, there are no suitable MM cell lines available that express high level of IGFBP7 to prove the specificity of anti-tumor effect of pcDNA3.1-IGFBP7." (PMID 20158915, 2010). "An added benefit of the anti-IGFBP7 sdAb-targeted bimodal NPs developed in this study is the possibility of using MRI to non-invasively assess tumour angiogenesis." (PMID 20959824, 2010). "Most importantly, it had a lasting effect on tumor development, being effective for at least 20 days, because stable expression of IGFBP7 by using pcDNA3.1-IGFBP7." (PMID 20158915, 2010). "Anti-IGFBP7 sdAb-PEGylated NPs-Cy5.5 fluorescence signal in the tumour region diminished after 24 h." (PMID 20959824, 2010). "The expression of IGFBP7 in tumour tissue correlated significantly with the response to IFN-α/5-FU therapy." (PMID 20407444, 2010). "The possible explanation for this phenomenon was attributed to the high performance of PCMV promoter contained in pcDNA3.1-IGFBP7, which would exhaust and be toxic to tumor cells since it ad infinitum synthesized IGFBP7." (PMID 20158915, 2010). "This mouse model is thus suitable for in vivo assessment of tumour targeting/imaging using anti-IGFBP7 sdAb." (PMID 20959824, 2010). "Meanwhile augmentation of IGFBP7 in cell supernatant would induce apoptosis of part of tumor cells and therefore, the synthesis of IGFBP7 also decreases with reduction of tumor cells." (PMID 20158915, 2010). "In consistent with our findings, the tumor suppressor roles of IGFBP7 in cervical cancer, osteosarcoma, prostate cancer, and breast cancer were discovered by other laboratories." (PMID 20433702, 2010). "All these findings strongly supported that IGFBP7 played a potential tumor suppressor role against colorectal carcinogenesis." (PMID 20433702, 2010). "In surgically removed human GBM tissue, IGFBP7 immunoreactivity colocalised with highly abnormal tumour vasculature stained with Ulex europeaus agglutinin I (UEA I), shown previously to selectively bind to carbohydrates of human brain vessels." (PMID 20959824, 2010). "Together, these results suggest that IGFBP7 plays different roles in different tumor or host environments." (PMID 20158915, 2010). "IGFBP7 accumulates in the basement membrane of the tumour endothelium, where it can bind to collagen type II, IV and V, heparin sulphate proteoglycans and other cytokines." (PMID 20959824, 2010). "As IGFBP7 has been shown to suppress tumour activity through induction of apoptosis, we evaluated the extent of apoptosis induced at 24 h after treatment of PLC-P/shRNA with 1000 IU ml−1 IFN-α." (PMID 20407444, 2010). "In vivo, intravenously injected anti-IGFBP7 sdAb-Cy5.5 bound to GBM vessels creating high imaging signal in the intracranial tumour." (PMID 20959824, 2010).
tumor (continued). "Together, the IGFBP7 and ER data and the tumour repopulation assays confirm the stem cell-like properties of cells in the SP." (PMID 20145614, 2010). "Among these genes with tumor suppressor function, insulin-like growth factor binding protein 7 (IGFBP7) appears to play an outstanding role." (PMID 19642975, 2009). "Immunohistochemistry showed high expression of INHBA and NEK6 proteins in 14 of 20 and 24 of 27 tumour tissues, respectively, whereas IGFBP7 and LUM proteins showed little immunoreactivity in tumour tissue relative to adjacent healthy tissue (data not shown)." (PMID 18827816, 2008). "Notably, we identified Vesicle-associated membrane protein-associated protein A (VAPA) as a key mediator in the transport of IGFBP7 vesicles to lysosomes, facilitating IGFBP7 degradation and thereby attenuating its tumor-suppressive function." (PMID 41692778, 2026). "Importantly, we provide mechanistic insights into how IGFBP7 modulates the tumour immune microenvironment to mediate immunotherapy resistance." (PMID 39788916, 2025). "Furthermore, our drug response prediction analysis identified several chemotherapeutic agents, including Nutlin‐3a, Dactolisib and Rapamycin, potentially more effective in STAD tumours with high IGFBP7 expression." (PMID 39788916, 2025). "Additionally, the role of IGFBP7 in cancer has been extensively studied, with several reports confirming its overexpression in tumor vasculature and some human cancer cell lines." (PMID 40943530, 2025). "TGF-β, secreted by cancer cells or other cell types in the surrounding microenvironment, also encourages GBM neovascularization, mainly by augmenting the levels of the pro-angiogenic factor insulin-like growth factor-binding protein 7 (IGFBP7) in the tumor endothelial fraction." (PMID 40141406, 2025). "Importantly, IGFBP7 expression was significantly negatively correlated with tumour TMB and stemness." (PMID 39351597, 2024). "IGFBP7 has been reported to play different roles in various tumours." (PMID 39351597, 2024). "Furthermore, IGFBP7 Q1 tumors were clearly defined by low or absent expression of these genes, implying that the stromal component of the tumor is crucial for IGFBP7 expression." (PMID 39362991, 2024). "LSCC showed strong IGFBP7 expression primarily in the invasion front of the tumor." (PMID 38893148, 2024). "Based on the pancancer expression analysis, IGFBP7 exhibited significant tumour‐type specificity." (PMID 39351597, 2024). "Furthermore, expression of IGFBP7 mutants that lose CD93 binding in tumors did not increase vessel densities as seen in tumors expressing WT IGFBP7, implicating a role of IGFBP7 in upregulating tumor angiogenesis via CD93." (PMID 38468017, 2024). "For example, IGFBP7 was previously reported to act as an oncogene in some cancers, but also exhibited tumor-suppressing properties in others." (PMID 39045455, 2024). "Regarding IGFBP-7, this peptide is a well-known tumor suppressor." (PMID 38541155, 2024). "The role of IGFBP7 in pathological tumor vasculature is thus reviewed separately." (PMID 39045455, 2024). "IGFBP7 was mainly located at the invasion front of the tumor." (PMID 38893148, 2024). "Blockade of the interaction with anti-IGFBP7 antibody similarly reduced tumor growth while promoting tumor vessel maturation, as evidenced by increased pericyte coverage and reduction in integrin β1/CD29 activation, a marker of EC destabilization and vascular leakiness." (PMID 38468017, 2024). "Our data indicate that IGFBP7 expression is either neutral to immune activation or is positively correlated with immune depletion in the tumor depending on whether immune gene signatures or ECOTYPER was used to profile the immune components of the tumors." (PMID 39362991, 2024). "Tumor tissue composition in relation to IGFBP7 expression was estimated by ECOTYPER30." (PMID 39362991, 2024).
tumor (continued). "In patients with metastatic carcinomas, IGFBP7 was reported to be highly expressed in circulating endothelial cells (CECs), where the number of CECs correlated with the degree of tumor angiogenesis." (PMID 39045455, 2024). "Additionally, immunohistochemical analysis of clinical GC samples also revealed significant upregulation of IGFBP7 in tumour tissues." (PMID 39351597, 2024). "IGFBP7 was predominantly expressed in the invasion front of the tumor." (PMID 38893148, 2024). "Bioinformatics analysis revealed that IGFBP7 expression was related to patient prognosis, tumour clinicopathological characteristics, tumour stemness, microsatellite instability and immune cell infiltration, as well as the expression of oncogenes and immune checkpoints." (PMID 39351597, 2024). "However, despite a wealth of studies elucidating the significant role of IGFBP7 in tumor development, its specific mechanisms and roles in different types of cancer still require further investigation." (PMID 39081862, 2024). "IGFBP7 may have tumour type‐specific effects on cancer and may even exhibit contradictory effects in some tumours." (PMID 39351597, 2024). "Furthermore, IGFBP7 is positively associated with inflammation-related pathways, ECM, and it is associated with various infiltrating immune cells, especially tumour-associated macrophages." (PMID 37660019, 2023). "Moreover, the IGFBP7 expression level was inversely related to tumour size and positively related to overall survival." (PMID 37660019, 2023). "At high magnification (60×), it could be seen that IGFBP7 was deposited in the area of CAFs and partially deposited around tumor cells, indicating that it may act on tumor cells." (PMID 37568781, 2023). "This suggests that IGFBP7 affects tumor progression in multiple ways." (PMID 37568781, 2023). "A Drosophila orthologue of IGFBP7, Ecdysone-inducible gene L2 (ImpL2), antagonizes Drosophila insulin-like peptides essential for cell growth and metabolism to induce the wasting phenotype in tumor-hosting adults." (PMID 37626857, 2023). "Our results revealed that IGFBP7 is primarily expressed in the tumor stroma." (PMID 37568781, 2023). "Additionally, IGFBP7 expression is positively correlated with tumor invasion depth, lymph node metastasis, distant metastasis/recurrence, and pathological staging in GC patients." (PMID 37568781, 2023). "Hindering the CD93-IGFBP7 axis by CD93 or IGFBP7 mAb could normalize tumor vasculature to suppress tumor growth." (PMID 37483608, 2023). "The contrary effect might occur because of different forms of IGFBP7 expression, including its expression on tumor cells and its expression in the extracellular matrix (ECM)." (PMID 37660019, 2023). "Likewise, the in vivo assays also found that IGFBP7 plays a tumor-promoting and pro-metastatic role in GC." (PMID 36681667, 2023). "Notably, fibroblasts in tumor tissue exhibited significantly higher expression levels of IGFBP7 compared to those in normal tissue (p < 0.0001)." (PMID 37568781, 2023). "Additionally, TIMP3, SPARC, IGFBP3, and IGFBP7 were highly expressed in the Mac_5 cluster, and these genes were involved in immunosuppression, tumor cell proliferation, and angiogenesis." (PMID 37533434, 2023). "Combination of IGFBP7, IDH mutation and tumor grade achieved better prognostic effects of LGG." (PMID 36043552, 2023). "Among them, IGFBP7, an important molecule, plays an important role in tumor development." (PMID 37568781, 2023). "Therefore, our study clarified that in the tumor microenvironment, tumor-cell-derived TGF-β1 induces the appearance of the IGFBP7+ CAF subgroup, and its higher IGFBP7 extracellular secretion level accelerates the progression of tumors." (PMID 37568781, 2023). "Moreover, the use of monoclonal antibodies able to block CD93/IGFBP7 interaction in mouse tumor models promoted vascular maturation, reducing tumor hypoxia and increasing tumor perfusion." (PMID 37443812, 2023).